MUC1 (mucin 1, cell surface associated)
Diseases named in the same sentence as MUC1 in open-access papers (continued):
Sharing a sentence is not in itself a finding about the gene and the disease.
cancer (continued). "WT1 and MUC1 were ranked as the two most highly immunogenic peptides in a variety of cancer tissues." (PMID 24649223, 2013). "MUC1 glycoproteins carrying poly-N-acetyllactosamine attenuated the interaction of the cancer cells with NK cells, resulting in decreased secretion of granzyme B by the NK cells." (PMID 23165940, 2013). "In fact, it is easy to see that as MUC1 expressing cancer cells emerge, the Th2 response becomes set." (PMID 26343966, 2013). "The Lewis y antigen increases MUC1 expression, thereby increasing the invasive and anti-apoptotic nature of cancer cells and their resistance to cytotoxic chemotherapies." (PMID 23708102, 2013). "Both pharmacological and immunotherapeutic strategies based on MUC1 to treat cancer should now be actively pursued." (PMID 23509794, 2013). "Attempts to develop MUC1-targeting cancer vaccines based on carrier-conjugated unglycosylated MUC1 tandem repeat peptides or carrier-conjugated glycosylated epitopes have been largely unsuccessful." (PMID 26343966, 2013). "Aberrant glycosylation of MUC1 and overexpression of Tn- and sTn-MUC1 forms starts early in cancer development and gets progressively more abundant with fewer sugars added to the glycosylation sites as tumors progress to later stages." (PMID 24072600, 2013). "The oncoprotein MUC1 inhibits ROS accumulation and ATP depletion in tumour cells under glucose-deprived conditions and promotes cancer cell survival." (PMID 23301705, 2013). "The sections were examined immunohistochemically with primary antibodies using the streptavidin peroxidase complex method, which revealed carcinoma cells positive for epithelial membrane antigen (EMA) and MUC-1." (PMID 23607038, 2013). "MUC1 is a transmembrane glycoprotein, and is the most intensively studied member of the mucin family, making MUC1 overexpression one of the more common alterations in human cancers." (PMID 23101681, 2012). "In the univariate analysis, MUC1 and MSLN expression were associated with aggressive cancer biology (i.e. short survival group) and MUC2 expression was associated with favorable biology (i.e. long survival group)." (PMID 22792233, 2012). "These variables would be important to consider since specific glycoforms of MUC1, bearing Tn, STn, sialyl-Lewisa and/or sialyl-Lewisx antigens have been detected in different types of cancer." (PMID 24970145, 2012). "MUC1 is able to break immune tolerance and both humoral and cell-mediated immune responses against MUC1 have been detected in cancer patients." (PMID 23166757, 2012). "DegMUC1 is therefore optimal for inclusion in human cancer vaccines aiming at inducing MUC1 specific CTL responses." (PMID 23189185, 2012). "Here in this study, we developed a novel MUC1 aptamer, and evaluated its capacity for delivering doxorubicin to cancer cells in vitro." (PMID 22384115, 2012). "The peptide inhibitor GO-201, which contains the CQC motif, has been designed and tested in a number of cancer cells to block oligomerization of MUC1 and thus inhibit its signaling activity and function." (PMID 22912777, 2012). "In this study, we predicted glycan epitopes expressed by a cancer-derived mucin, MUC1, by computational glycomics." (PMID 23023583, 2012). "MUC1 transgenic (MUC1.Tg) mice have widely been used as model recipients of cancer immunotherapy with MUC1." (PMID 23028615, 2012). "MUC1 is the best-characterized membrane-bound mucin that is expressed in most epithelial cells and is aberrantly overexpressed in various cancers, including breast, ovarian, lung, colon, and pancreatic carcinomas." (PMID 22962849, 2012). "This is in accordance with our previous finding of strong IgG responses to GalNAc MUC1 in human MUC1 transgenic mice and cancer patients." (PMID 23189185, 2012). "MSLN and MUC1 were highly significant predictors of early cancer-specific mortality, and were superior to conventional pathologic features as prognostic markers." (PMID 22792233, 2012).
cancer (continued). "Addressing overexpressed gene products like aminopeptidase N-α-V-β-3 or MUC-1 in (breast) cancer tumor cells is highly recommendable for optical imaging approaches, since these are also prognostic markers." (PMID 22605971, 2012). "MUC1 transgenic (MUC1.Tg) mice, which were generated to investigate the optimal use of MUC1 in cancer immunotherapy, are known to be immunologically tolerant to MUC1." (PMID 23028615, 2012). "Understanding how MUC1 regulates cell function continues to occupy current research efforts and the importance of MUC1 as an oncogene is highlighted by the fact that it is the subject of vaccine development for treatment of several human cancers." (PMID 22905162, 2012). "Because the MAG gene up-regulation was found in cancer cells grown as a co-culture with the CAFs, the expression of MUC1 (which binds MAG) was examined immunohistochemically." (PMID 22453032, 2012). "Secondary endpoints are overall survival (OS) time, safety, tolerability, RFS/OS in MUC-1 positive cancers." (PMID 22494623, 2012). "MUC1 is a large transmembrane glycoprotein and oncogene expressed by epithelial cells and overexpressed and underglycosylated in cancer cells." (PMID 22905162, 2012). "In this study, a novel MUC1 aptamer is exploited as the targeting ligand for carrying doxorubicin (Dox) to cancer cells." (PMID 22384115, 2012). "Our findings that the hypoxic organoids have reduced expression and deviant localization of HMFG/MUC1, further strengthens the conclusion that the hypoxic mammary epithelial cells adopt an immature and cancer-like phenotype." (PMID 23029547, 2012). "Of particular importance, the mucin MUC1 is overexpressed in numerous cancers including breast, ovarian, lung, pancreatic, prostate, gastric, and colorectal, where high expression generally correlates with increased mortality rates." (PMID 22866263, 2012). "The purpose is to overcome the immune suppression seen in cancer subjects and thus to enhance the development of an effective immune response to the MUC1 immunogen present in the vaccine." (PMID 22494623, 2012). "Previous reports have shown that MUC1 is overexpressed during the progression of human PC and it plays an important role in cancer invasion and metastasis." (PMID 23102107, 2012). "Together, these results demonstrate that the MUC1 intracellular domain is both necessary for EGF-induced carcinoma cell migration on vitronectin and sufficient to drive cell migration on vitronectin and metastasis in the absence of EGF." (PMID 22586492, 2012). "MUC1 is known to be over-expressed by various human carcinomas and is shed into the circulation where different epitopes can be detected in the serum of patients by specific anti-MUC1 antibodies." (PMID 23241107, 2012). "In conventional carcinomas MUC1 is largely apical, with intracytoplasmic or intercellular distribution." (PMID 22217342, 2012). "Previous work using this method showed that the mucins MUC1, MUC5AC, and MUC16 are major cancer-associated carriers of the CA 19-9 antigen in the blood." (PMID 22220206, 2011). "MUC1 has been extensively studied as a target antigen for the immunotherapy of cancer, and some modest clinical responses have been reported." (PMID 24212946, 2011). "MUC1 protein is overexpressed and aberrantly glycosylated on the surface of most adenocarcinoma cells, making it a very attractive target for cancer therapy." (PMID 21912664, 2011). "MUC1 VNTR variants have been related to alterations in both T-antigen presentation and in the local immune response in cancer." (PMID 22039891, 2011). "This is the case of MoAbs directed against antigens that are homogenously overexpressed by cancer cells such as MUC1 and CA125." (PMID 22235224, 2011).
cancer (continued). "Unglycosylated MUC1, or undefined glycoforms of MUC1, has been used in other ELISA based assays for detecting antibodies in sera from cancer patients." (PMID 21385452, 2011). "MUC1 is associated with cellular transformation and tumorigenicity and is considered as an important tumor-associated antigen (TAA) for cancer therapy." (PMID 21931707, 2011). "The ability to stimulate the generation of antitumor CD8+ T cells seemed to be more pronounced in HER2+ cancers, especially towards Her2-, trag-3-, muc-1-, and bcl-xL-derived epitopes." (PMID 22112244, 2011). "MUC1 is overexpressed in almost 95% of cancer cells, a molecular pathological feature that is associated with carcinogenesis and poor prognosis." (PMID 22073229, 2011). "We have developed a novel O-glycopeptide array-based assay detecting IgG autoantibodies to specific glycoforms of MUC1, which has low backgrounds and detects autoantibodies in sera from cancer patients." (PMID 21385452, 2011). "With overexpression of MUC1 in cancer cells, the MUC1-C subunit accumulates in the cytoplasm and is targeted to the nucleus, where it contributes to the regulation of gene expression." (PMID 22140559, 2011). "The mucin 1 (MUC1) protein is overexpressed in most human carcinomas and certain hematologic malignancies, making it one of the more common alterations in human cancers." (PMID 22140559, 2011). "MUC1 is overexpressed and aberrantly glycosylated in carcinomas and in certain hematological malignancies." (PMID 24212946, 2011). "In most cancers of glandular epithelial origin, MUC1 is overexpressed and aberrantly glycosylated, leading to exposure of highly immunogenic truncated carbohydrate structures." (PMID 20735851, 2010). "On cancer cells, MUC1 also loses its apical polarization and becomes expressed over the entire cell surface." (PMID 20565834, 2010). "Next, a photosensitizing agent chlorin e6 was coupled to the 5’ amino group of the MUC-1 aptamers and targeted to cancer cells expressing the aberrant MUC-1 glycoforms." (PMID 27713328, 2010). "While the presence of these immune complexes has prognostic significance in cancer patients, the significance of free AAbs to MUC1 is less clear." (PMID 21113302, 2010). "This inability to detect membrane bound MUC1 because of glycosylation differences is documented in the literature where the presence of MUC1 on hematopoietic cells in patients having certain cancers was ignored for some time." (PMID 20806091, 2010). "On the other hand, in the EUS-FNA samples, the gene, CDK2A, CD44, S100A4 and MUC1 were specifically related to the 2nd clustering between cancer and non-cancer (p < 0.05)." (PMID 20416107, 2010). "MGL and DC-SIGN recognize cancer-specific glycosylation changes of the mucin MUC1, in particular the carbohydrate sialyl LewisX and the sialyl TN epitope; MUC1 and TAG-72 bind also the MR." (PMID 21331365, 2010). "Aptamers generated against the MUC-1 glycoforms have recently been used to deliver drugs into cancer cells." (PMID 27713328, 2010). "On the basis of the histological classification of ACs, we found that CK20 had a high sensitivity for the histological intestinal type and MUC1 had high sensitivity for the histological pancreatobiliary type carcinoma." (PMID 21106111, 2010). "Like other mucins, MUC1 protects and lubricates normal glandular epithelia, whereas MUC1 overexpression in cancer alters many cellular properties, including intercellular adhesion and immune recognition." (PMID 19175940, 2009). "The data indicate that Ad5AMUCH_RSV-NIS activity is stringently restricted to MUC-1-positive cancer cells." (PMID 19635153, 2009). "MUC1 cDNA has been used as a cancer vaccine in mouse models and has been shown to result in long-term growth suppression of tumors." (PMID 20034397, 2009). "MUC1 vaccines have also been used in several clinical trials wherein cancer patients were immunized with either synthetic peptides, or DCs transfected with MUC1 cDNA." (PMID 19534821, 2009).
cancer (continued). "Alterations in MUC1 glycosylation accompany the development of cancer and influence cellular growth, differentiation, transformation, adhesion, invasion, and immune surveillance." (PMID 19811637, 2009). "MUC1 increases ß-catenin levels in the cytoplasm and nuclei of carcinoma cells by blocking its degradation, resulting in an increase in cell proliferation." (PMID 19816567, 2009). "NM23, which was shown to be an activating ligand of MUC1* on cancer cells, co-localizes with MUC1* on pluripotent cells." (PMID 18833326, 2008). "Fluorescent imaging revealed that MUC1* is the predominant form of protein on cultured cancer cells and is uniformly distributed over the entire cell surface." (PMID 18446242, 2008). "Mouse models have been integral to the current understanding of the role of MUC1 in the development and progression of cancer of the mammary epithelium (note that the human homolog is written MUC1 and the mouse Muc1)." (PMID 21655373, 2008). "This confirmed that the proteins in the cancer cell supernatants that were immunoprecipitated with MUC1*1110-ecd peptides were indeed NM23." (PMID 18446242, 2008). "We performed similar experiments by treating MUC1-positive cancer cells as well as MUC1 and MUC1*1110 transfected cells with Anti-MUC1*." (PMID 18446242, 2008). "The membrane mucin MUC1 is aberrantly expressed in a variety of cancers, and in stomach, it is a ligand for Helicobacter pylori where it plays a role in gastric carcinogenesis." (PMID 19238635, 2008). "Our finding that the major species in cultured cancer cells and on cancerous tissues is MUC1*, the cleaved form, led us to wonder if MUC1 cleavage had any functional significance." (PMID 18446242, 2008). "As on cancer cells, MUC1* functions as a growth factor receptor on pluripotent embryonic stem cells." (PMID 18833326, 2008). "Anti-MUC1* has been used extensively in our labs to effectively identify and sort both live and fixed MUC1*-positive cancer cells using FACS." (PMID 18833326, 2008). "Herein, we report that a membrane-bound MUC1 cleavage product, that we call MUC1*, is the predominant form of the protein on cultured cancer cells and on cancerous tissues." (PMID 18446242, 2008). "Cleavage of MUC1 on cancer cells releases the bulk of the extracellular domain, including most if not all of the self-aggregation domain." (PMID 18833326, 2008). "Cultured cancer cells were analyzed by immuno-cytochemistry to determine the expression pattern of MUC1 and its cleavage product MUC1*." (PMID 18446242, 2008). "Taken together, these results demonstrate that the predominant MUC1 species on cancerous tissue, as on cultured cancer cells, is the cleaved species, MUC1*." (PMID 18446242, 2008). "Staining with Anti-MUC1* shows that, like on cultured cancer cells, the major form of MUC1 on cancerous tissues is MUC1*." (PMID 18446242, 2008). "We recently reported that a transmembrane cleavage product, MUC1*, is the predominant form of the protein on cancer cells." (PMID 18833326, 2008). "The expression of MUC1 in normal epithelial cells is confined to the apical surface, but covers the entire surface of many cancer cells." (PMID 17912239, 2007). "We examined the possibility of selecting specific antibody fragments from phage libraries against common cancer antigens available in our lab, including ED-B domain of fibronectin, MUC1 epithelial mucin, and CEA." (PMID 17945015, 2007). "On the one hand, overexpression of MUC-1 has been shown to increase the metastatic potential of the cancer cells." (PMID 17726465, 2007). "MUC1 is an oncoprotein whose overexpression correlates with aggressiveness of tumors and poor survival of cancer patients." (PMID 16846534, 2006).
cancer (continued). "In addition, the levels of p-ERK and p-Akt were reduced by anti-MUC1 antibody in all three cancer cell lines." (PMID 41516394, 2026). "Finally, to study the activation of complement system in association with MUC1 expression, we evaluated the deposition of PTX3 and C3 in cancer tissue." (PMID 41533164, 2026). "Consequently, when cancer cells detach, MUC1 aids in sustaining signals that promote survival pathways, ultimately enhancing their metastatic potential." (PMID 40655139, 2025). "Widely expressed in many cancer types, MUC1 is heavily studied in cancer biology research." (PMID 40699805, 2025). "Specifically, MUC1 promotes the expression of multidrug resistance (MDR) genes, including ABCC1, which encodes the MRP1 protein, thereby facilitating the exodus of chemotherapeutic drugs from cancer cells." (PMID 40699746, 2025). "However, dysregulated and inappropriately glycosylated MUC1 have been correlated with chronic epithelial diseases and cancers, suggesting that the perturbation of the general function of this glycoprotein can alter tissue homeostasis." (PMID 41295249, 2025). "The results showed that inhibition of MUC1 could be effective in reducing or blocking cancer growth by fisetin treatment." (PMID 39926326, 2025). "Consequently, enhancing MUC1-specific immunity through approaches such as vaccines, MUC1-targeted antibodies, or T-cell therapies is a promising strategy in cancer treatment." (PMID 40333213, 2025). "Thus, the authors revealed that MUC1 expression was associated with aggressive pathological features, and they suggested MUC1 as a useful prognostic marker for predicting cancer outcomes." (PMID 41154387, 2025). "The cell surface-associated glycopeptides and extracellular signals derived from the proteolytic processing of MUC1 on the cancer cells alter the cytotoxicity and migration of natural killer (NK) cells and T-cells by modulating NK group 2D (NKG2D) ligands and β-catenin, respectively." (PMID 40699805, 2025). "Because of the importance of mucins and O-glycosylation in human health and diseases such as cancer, the Paulsen group synthesized more than 200 peptides and glycopeptides derived from MUC1 to 4 and other glycoproteins for studies of their biological role and pathways of O-glycan biosynthesis." (PMID 41011627, 2025). "MUC1 mAbs against TA epitopes pose an interesting option to selectively target the cancer cells in PDAC; whether IgA mAbs can effectively target MUC1 in cancer should be further evaluated." (PMID 40358156, 2025). "Additionally, in cancers, MUC1 glycosylation is reduced and altered, and specifically modified glycoforms are formed." (PMID 41154387, 2025). "Studies have shown that MUC-1 is involved in cell proliferation, invasion, and migration and could be a potential molecule for cancer immunotherapy and targeted therapy." (PMID 39941799, 2025). "Additionally, MUC1 enhances the metabolic pathways that support cancer cell survival under chemotherapeutic stress." (PMID 40699746, 2025). "The glycosylation grade of MUC1 is essential for its functions in normal and cancer cells." (PMID 40001578, 2025). "Furthermore, NEAT1 is essential for the stability of the MUC1-CT protein, suggesting that NEAT1 probably helps to maintain the oncogenic activity of MUC1-CT in cancer cells." (PMID 40001578, 2025). "Furthermore, since cancer cells release MUC1, its measurement is very important as it allows us to monitor the clinical response of patients to therapy." (PMID 40001578, 2025). "The role of mucin in cancer metastasis has been characterized in MUC1 and MUC16." (PMID 40699805, 2025).